CD82 (CD82 molecule)
Diseases named in the same sentence as CD82 in open-access papers (continued):
Sharing a sentence is not in itself a finding about the gene and the disease.
tumor (continued). "It appears that high tetraspanin levels, namely CD82 and CD9, are related to tumor growth inhibition, as studies have demonstrated that in some late-stage tumors, such as colorectal cancer, these tetraspanins are downregulated and therefore associated with poor prognosis." (PMID 34830819, 2021). "KAI1/CD82 is a well-characterized metastasis suppressor of various solid malignant tumors without affecting primary tumor growth and a recognized biomarker to predict metastatic potential." (PMID 34306081, 2021). "We also provide evidence that RelA/p65′s tumour promoting action in NSCLC is due to, at least in part, the downregulation of CD82 that inhibits cell migration and EMT, and the stimulation of ERK and Rac1 through the engagement of integrin-mediated signalling as revealed by bioinformatics analysis." (PMID 34503110, 2021). "Considering its pathological and physiological significance, KAI1/CD82 could be a potential strategy for clinical predicting and preventing tumor progression and metastasis." (PMID 34306081, 2021). "Our results indicated that CD82 could directly interact with ADAM17 and influence its protease activity, which refreshed our current knowledge about the mechanism of CD82 as a tumor metastasis suppressor." (PMID 33204367, 2020). "In line with this, knockdown of CD82 expression by sh/CD82 or miR-197 in Drosha-silenced MGC-803 cells resulted in the increased expression of p-EGFR, p-ERK1/2 and MMP7, which rendered the tumor cells with a marked invasive potential." (PMID 28252644, 2017). "Although previous studies showed that CD82 functions as a suppressor tumor gene in various carcinomas, the function of CD82 in RCC have not been reported." (PMID 28881668, 2017). "Overall, studies of KAI1/CD82, CD44, MMP7 and β-catenin in relation to tumor metastasis indicate that these molecules are involved in the process of tumor progression through regulating the intercellular adhesion; However, there are few studies on the interaction between them." (PMID 26408312, 2015). "HGF stimulation of PTC cells causes prompt phosphorylation of Met protein, stimulates the migratory/invasive capacity of tumor cells, up-regulates the expression of the pro-invasive molecule cyclo-oxygenase 2, and down-regulates the anti-metastatic protein KAI-1/CD82." (PMID 28548071, 2014). "Splice variants generated with some of those specific intron junctures in CD82 and TSPAN 32 from group CD63L have been reported in normal and tumor tissues and from TSPAN17, TSPAN 31 from groups TSPAN15L and TSPAN13L (mRNA variants hApr07 and jApr07 from NCBI AceView) respectively." (PMID 19262691, 2009). "Specifically, miR‐31 directly targets the tumour suppressors CCAAT enhancer binding protein α (CEBPA) and dachshund family transcription factor 1 (DACH1), which decreases β‐catenin protein level via increasing Wnt/β‐catenin signalling inhibitors, such as AXIN1, CD9 and CD82." (PMID 38797942, 2024). "Further, liprin-α1 expression in TILs did not correlate with CD82 expression in tumor cells." (PMID 37335526, 2023). "The relationship between CD82 palmitoylation mutation and EGFR and c-Met has not been clarified so far, including the theoretical mechanism for its expression and localization changes in tumor cells and specific metabolic pathways." (PMID 35538033, 2022). "CD82 was identified as a component of the cell surface TIMP1-interacting protein complex by directly binding to Timp1 amino-terminal region through its large extracellular loop domain and, it was shown to co-localise with Timp1 in cancer cell lines and tumour tissues." (PMID 34503110, 2021).
tumor (continued). "In a mouse xenograft model, it was shown that enforced expression of KAI1/CD82 could repress lung metastasis of AT6.1 cells without affecting the growth rate of the primary tumor." (PMID 34306081, 2021). "CD82 may stabilize or strengthen E-cad-dependent intercellular adhesion by regulating β-catenin-mediated signal transduction on NSCLC cells and prevent cancer cells from seceding from the primary tumor site." (PMID 34306081, 2021). "CD8+ TILs were increased in the intra- and peri-tumoural compartment of CD82 negative tumours." (PMID 34503110, 2021). "It was demonstrated that compared with the control group, tumor growth was not suppressed when mice were injected with KAI1/CD82+ EPCs (endothelial progenitor cells), but the incidence of lung metastasis and the number of metastatic foci on the lung surface were significantly reduced." (PMID 34306081, 2021). "Therefore, by down-regulating the expression of these tumor suppressor genes including Smad4, CD82 and PTEN through cellular miRNAs, a persistent HCV infection could eventually lead to tumor development and metastasis in liver." (PMID 19671175, 2009). "In addition, the disease-free survival rate of patients with KAI1/CD82-positive tumours was significantly higher than that of patients with KAI1/CD82-negative tumours (77.1 vs 42.3%, P=0.004)." (PMID 12838318, 2003). "Complementing EMT-promoting transcription factors, several metastasis suppressor genes (MSGs), such as CADM1, BRMS1, and KAI1/CD82, function to restrict metastatic dissemination without affecting primary tumor growth." (PMID 41409250, 2025). "For both subsets of γδ TRM, ZNF683 (Hobit), CD81, CD82, and IFNG expression is higher in the tumor compared to normal tissue." (PMID 39454432, 2024). "Positive expressions of CD133, CD82/KAI1, and VM were significantly correlated with pTNM stage and tumour relapse but not with gender, age, or tumour numbers." (PMID 37052868, 2023). "KAI1/CD82, a member of tetraspanin superfamily of glycoproteins, has been reported as a tumor metastasis suppressor gene in various types of cancers without affecting the tumor formation." (PMID 34306081, 2021). "Because CD82 acts as a metastasis suppressor and interacts with CD8, although we showed that CD8+ TILs were increased in CD82 negative tumours, this difference was not statistically significant, suggesting that the suppressing activity of CD82 may not be related to the recruitment of CD8+ TILs." (PMID 34503110, 2021).
cancer (121 papers, 1999 to 2025). A tumor composed of atypical neoplastic, often pleomorphic cells that invade other tissues. "The metastasis suppressor gene CD82 has been implicated in several cancers to inhibit cell migration through restricting cell protrusion and retraction." (PMID 41028875, 2025). "The expression of KAI1/CD82 tends to be altered in different cancers and has been linked to survival term of patients." (PMID 34121877, 2021). "The downregulation of CD82 expression is associated with advanced stages of several human cancers and correlates with the acquisition of metastatic potential." (PMID 29760437, 2018). "More recent studies have demonstrated that loss of CD82/KAI1 expression is correlated with poor prognosis of several cancers, reviewed in Ref." (PMID 29946318, 2018). "CD82/KAI1, a member of the tetraspanin family, is a cancer metastasis suppressor that has been implicated in diverse biological processes, including fusion, adhesion, migration, apoptosis, and cell morphology alteration." (PMID 29760437, 2018). "CD82, also known as KAI-1, belongs to tetraspanin family associated not only with extensive physiological processes, but also in pathological situations such as cancer invasion and metastasis." (PMID 28881668, 2017). "According to immunohistochemistry results of 32 patients in this study, we believe that defects in the N-terminus of TIMP-1 and CD82 endocytosis deficiency are both responsible for cancer development." (PMID 28030805, 2017). "Decreased levels of KAI-1/CD82 have been linked to limited cancer cell invasiveness and the suppression of metastatic cell growth mainly through inhibition of β-catenin-mediated EMT." (PMID 27126599, 2016). "Down-regulation or loss of KAI1/CD82 has been associated with metastatic progression and poor prognosis in many human cancer types." (PMID 25605251, 2015). "KAI1/CD82 is widely expressed in human tissues, and downregulation of this gene is associated with the metastatic phenotype of several malignancies, including carcinomas of the prostate, lung, colon, pancreas, stomach, liver and bladder." (PMID 23420768, 2013). "The cytoskeletal abnormality in KAI1/CD82-expressing cancer cells causes the attenuation of both cellular protrusion and retraction processes, which ultimately leads to the suppression of cell movement." (PMID 23251627, 2012). "Future studies should map the precise molecular cascade linking palmitoylation-deficient CD82 to mitochondrial outer membrane permeabilization and explore whether this mechanism extends to other therapy-resistant cancers." (PMID 41415560, 2025). "Low KAI1/CD82 activity is associated with metastasis and a poor prognosis for cancers." (PMID 37553596, 2023). "Additionally, high levels of CD9 and CD82 have been associated with a favorable prognosis in different types of cancers, like breast, pancreas, prostate, and lung cancer." (PMID 34830819, 2021). "Future studies are still needed to fully explicate the role of KAI1/CD82 in certain cancers and also address whether KAI1/CD82 downregulation is a cause or consequence of the progression of cancer." (PMID 34306081, 2021). "Some tetraspanins, including CD82, have been associated with cancer progression." (PMID 34445169, 2021). "CD82 is a ubiquitously expressed transmembrane protein which has been implicated in a vast number of biological functions such as immune-response, differentiation, cancer growth and metastasis." (PMID 32483464, 2020). "Additionally, the palmitoylation‐deficient human tetraspanin CD82 lost the function of inhibition of cancer cell migration and invasion (Zhou, Liu, Reddivari, & Zhang, 2004)." (PMID 31406958, 2019). "In malignant solid tumours, the detection of CD82 expression indicates a better prognosis for cancer patients, whereas the downregulation or loss of CD82 expression is commonly associated with clinically advanced cancers." (PMID 23076981, 2012).
cancer (continued). "Conversely, early loss of CD82 expression during carcinoma formation may contribute to release this constraint inducing migration of epithelial cells and can explain part of the metastasis-suppressor functions of CD82." (PMID 34207462, 2021). "Promoter hypermethylation, gene mutations and loss of heterozygosity only infrequently provoke CD82 downregulation in cancers, although reduced CD82 promoter activity due to aberrant availability of specific transcription factors might account for this process 38-42." (PMID 32483464, 2020). "The squamous differentiation marker ΔNp63α enhances metastatic potential through CD82-mediated modulation of bone microenvironment adhesion and cancer stemness." (PMID 40746833, 2025). "The number of EVs expressing CD82 can forecast cancer prognosisby disclosing the potential for metastasis; fewer CD82+ EVs can point to an increased chance of metastasis in cancers, servingas a useful predictor of outcomes." (PMID 40720603, 2025). "The results emphasize the importance of palmitoylation in KAI1/CD82's role in inhibiting cancer cell migration and invasion." (PMID 40977744, 2025). "CD82 is a transmembrane protein that is considered a metastatic oncogene and plays a key role in cancer recurrence." (PMID 40299574, 2025). "The metastasis suppressor cd82 is known to reverse EMT process in cancer cells by inhibiting the TGF-β1/Smad andWnt/β-catenin pathways." (PMID 39061080, 2024). "According to a review of 64 studies, 83% of them reported that CD82 expression was downregulated in cancer tissues." (PMID 38473906, 2024). "Our transcriptomic data align with existing studies that have identified genes like NPTX1, TRIM31, and CD82/KAI1 as potential therapeutic targets in various cancers." (PMID 37958599, 2023). "This is a challenging problem because the KAI1/CD82 metastasis suppressor is known to be epigenetically silenced in at least 15 solid human tumors and possibly a few hematopoietic human malignancies." (PMID 37990044, 2023). "It has further been discovered that liprin-α1 inhibits CD82 in cancers of the breast and of the head and neck region." (PMID 37335526, 2023). "The expression of CD82 upon transition from the endothelial to the hematopoietic program is an interesting finding, as CD82 is a well-known suppressor of cell motility and cancer metastasis." (PMID 37694151, 2023). "CD82 has been found to be a metastatic suppressor and shown to suppress migration and/or invasion of cancer cells." (PMID 36291767, 2022). "Numerous studies have reported that CD82 is downregulated in malignant tumors of various organs, including the lung, breast, ovary, and liver." (PMID 36386228, 2022). "In particular, evidence suggests that CD82/KAI-1 is a metastasis suppressor factor in several cancers, and miR-197 seems to indirectly activate two genes that induce cellular metastases, ROCK, and Rac 1, through direct action in CD82/KAI-1." (PMID 36143221, 2022). "Several previous studies also demonstrated that CD82 represses TGF-β1-mediated EMT through regulation of different signaling pathways in various carcinoma types." (PMID 36386228, 2022). "The levels of the tetraspanin CD82 are indirectly proportional to the patient’s prognosis in many types of cancers, like gastric, colorectal, lung, breast, bladder, prostate, and endometrial cancer and others." (PMID 34830819, 2021). "A large number of experiments have shown that the differentially expressed KAI1/CD82 is closely related to malignant tumors, which can be served as a biomarker in tumors." (PMID 34306081, 2021). "CD82 is a member of the tetraspanin protein family and is known as a suppressor of various cancer metastasis." (PMID 33953224, 2021). "The present review aims to discuss the role of KAI1/CD82 in metastasis for different cancers and examine its prospects as a metastasis biomarker and a therapeutic target." (PMID 34306081, 2021).
cancer (continued). "CD9 (Tspan29), CD63 (Tspan30) and CD82 (Tspan27) inhibit metastasis of various cancers, whereas Tspan8 and CD151 (Tspan24) promote metastasis." (PMID 33955149, 2021). "It has been reported that CD82 can negatively regulate EMT in several other human cancers, such as non-small cell lung cancer and prostate cancer." (PMID 34540692, 2021). "We generated CD82-overexpressing A549 and H1437 cancer cells by transfection with either a control mCherry expression vector or the same vector carrying CD82 fused to mCherry (mCherry-CD82OE), followed by selection in G418 and FACS sorting." (PMID 34503110, 2021). "Overexpression of CD82 in cancer cells markedly reduced their migration ability/capacity compared to mCherry-vector control A549 and H1437 cells." (PMID 34503110, 2021). "It appears that the mechanism by which CD82 contributes to cancer progression is by altering the function of different types of molecules, such as integrins, growth factor receptors, c-MET, and uPAR." (PMID 34830819, 2021). "The results of our experiments and other studies proved the cancer metastasis suppressor role of CD82 and CD9, clinically connected to the progression, invasion, and metastasis of various malignancies." (PMID 32091301, 2020). "CD82 promotes integrin α6 internalization resulting thereby in reduced adhesion of cancer cells to laminin, and subsequent reduction of cell migration." (PMID 32483464, 2020). "CD82 has been well documented as an inhibitor of cell motility, invasion, and survival in cancer cells, with varied inhibition mechanisms." (PMID 33298014, 2020). "CD82, a member of tetraspanins, is a potent inhibitor of cancer metastasis in numerous malignancies." (PMID 32483464, 2020). "Numerous studies demonstrated that CD82 plays a pivotal role as inhibitor of cancer cells motility by interfering integrin-mediated cellular adhesion and migration 49-53." (PMID 32483464, 2020). "KAI1 (CD82) is a metastasis suppressor gene known to be down-regulated in carcinomas of breast, prostate and many other organs." (PMID 32986351, 2020). "Among those, CD9, CD82 and Tspan8 have critical roles in cancer metastasis manifested as altered expression levels." (PMID 30289336, 2019). "The results reveal liprin-α1 as a novel regulator of CD82, linking liprin-α1 to the cancer cell invasion and metastasis pathways." (PMID 30005669, 2018). "Liprin-α1 is a part of β1-integrin signaling and recycling, while CD82 modulates β1-integrin maturation and integrin-related cell adhesion in cancer cells, and is regulated by endocytosis and palmitoylation." (PMID 30005669, 2018). "Taken together, our GSEA data underlined the role of liprin-α1 in the cell edge functions of cancer cells during cell invasion, shown by modifications in CD82 expression as well as by rearrangements in actin cytoskeleton after liprin-α1 silencing." (PMID 30005669, 2018). "We present novel insight into liprin-α1 dependent regulation of different biological processes and of CD82 which links liprin-α1 to metastatic progression of cancer cells." (PMID 30005669, 2018). "When cancer cell invasion was examined using matrigel as a basement membrane barrier, the high CD82-expressing cells displayed decreased invasiveness as compared with the low CD82-expressing cells." (PMID 27926483, 2017). "The transmembrane protein CD82/KAI1 suppresses the metastatic potential of various cancer cell types." (PMID 27926483, 2017). "Its ability to inhibit cell motility, invasion and adhesion, together with the clinical observations that KAI1/CD82 expression is often lost/reduced in cancer, strongly suggests that KAI1/CD82 has an anti-oncogenic role in cancer." (PMID 26431493, 2015). "We first demonstrated that sialyl Lewis antigen synthesis is regulated by a CD82/KAI1-mediated system, and then examined the effects of this mechanism on cancer cell metastasis in a mouse metastasis model." (PMID 25923697, 2015).